CTNNB1 (catenin beta 1)
Diseases named in the same sentence as CTNNB1 in open-access papers (continued):
Sharing a sentence is not in itself a finding about the gene and the disease.
bone metastasis (3 papers, 2020 to 2025). Transfer of a neoplasm from its primary site to bones. "For OS, we considered sex, smoking history, bone metastasis, liver metastasis, CTNNB1 mutation, and MYC amplification." (PMID 41221800, 2025). "Our results showed that the AC/AA genotype of CTNNB1: rs1880481 was associated with a decreased risk of bone metastasis." (PMID 32453708, 2020). "Our results revealed that CTNNB1: rs1880481 with the AC/AA genotype was significantly associated with a lower risk of developing bone metastasis (p = 0.004)." (PMID 32453708, 2020). "The univariate Cox model analysis showed that the AC/AA genotype of CTNNB1: rs1880481 was significantly associated with a decreased risk of bone metastasis (HR = 0.729, 95% CI=0.585-0.907, p = 0.005)." (PMID 32453708, 2020). "Furthermore, when this univariate Cox model analysis was adjusted for KPS, BMI, disease stage and TNM stage, the result demonstrated that CTNNB1: rs1880481 with the AC/ AA genotype was also significantly correlated with a decreased risk of bone metastasis (HR = 0.742, 95% CI=0.592-0.929, p = 0.009)." (PMID 32453708, 2020). "When taking the distribution of risk genotypes of bone metastasis into account, we found that CTNNB1: rs1880481 with the AC/AA genotype (25.7%) had a lower ratio in bone metastasis patients than the CC genotype (74.3%)." (PMID 32453708, 2020). "In our study, we found that bone metastasis patients with CTNNB1: rs1880481 AC/AA genotype had a significantly lower Ki-67 index than those with the CC genotype." (PMID 32453708, 2020). "Our result demonstrated that patients with bone metastasis in NSCLC carrying the AA/AC genotype of CTNNB1: rs1880481 had a significantly lower level of SCC-Ag than patients with the CC genotype (p = 0.002)." (PMID 32453708, 2020). "Moreover, we attempted to explore the differences between gene mutation patients with bone metastasis in NSCLC and the SNP of CTNNB1: rs1880481." (PMID 32453708, 2020).
carcinoid (3 papers, 2012 to 2015).
Cerebral ischemia (3 papers, 2022 to 2025). Restriction of arterial blood supply to the brain associated with insufficient oxygenation to support the metabolic requirements of the tissue. "Downregulation of CTNNB1 after cerebral ischemia may inactivate the Wnt pathway, releasing inhibition of apoptosis and exacerbating inflammation through NF-κB activation." (PMID 40786625, 2025).
cerebral palsy (3 papers, 2023 to 2026). A group of disorders affecting the development of movement and posture, often accompanied by disturbances of sensation, perception, cognition, and behavior. "CTNNB1 monoallelic pathogenic variants account for up to 4% of genetically determined cerebral palsy cases, yet their phenotypic spectrum remains poorly defined." (PMID 41789168, 2026). "Genetic testing can identify the genetic etiology in approximately 40% of cerebral palsy cases, and recent studies have identified CTNNB1 as the most prevalent cause of misdiagnosis of cerebral palsy." (PMID 39935833, 2025). "We report two patients with CTNNB1-related neurodevelopmental disorder whose clinical features were similar to those of cerebral palsy, hindering diagnosis." (PMID 37416820, 2023).
colitis (3 papers, 2012 to 2025). Inflammation of the colon. "It has been also observed that the Bft toxin from ETBF induces colitis and disrupts CDH1 junction, activates CTNNB1 (beta catenin) signalling, and induces IL8 secretion in murine colonic epithelial cells (CECs)." (PMID 33937029, 2021).
Cushing syndrome (3 papers, 2021 to 2022). Cushing's syndrome (CS) encompasses a group of hormonal disorders caused by prolonged and high exposure levels to glucocorticoids that can be of either endogenous (adrenal cortex production) or exogenous (iatrogenic) origin. "CTNNB1 was enriched in four pathways: thyroid hormone signaling pathway, Wnt signaling pathway, Hippo signaling pathway and Cushing syndrome." (PMID 36292787, 2022). "CPA is the result of abnormal differentiation from ZF cells and is usually caused by somatic mutations of protein kinase cAMP-activated catalytic subunit alpha (PRKACA), GNAS complex locus (GNAS) and catenin beta 1 (CTNNB1), resulting in hypercortisolism and clinical Cushing’s syndrome." (PMID 34943980, 2021).
embryonal tumors (3 papers, 2023 to 2025). "CTNNB1 (beta-catenin) showed the highest expression in predominantly fetal tumors but in embryonal tumors as well." (PMID 40766612, 2025).
endometrial adenocarcinoma (3 papers, 2016 to 2022). "CTNNB1 mutations and subsequent nuclear accumulation of β‐catenin have been already reported in endometrial adenocarcinoma and in particular in foci of morular metaplasia." (PMID 34318590, 2022). "Mutations affecting the KRAS/GTP interface and those targeting the CTNNB1 interfaces with FBXW11 or BTCR are largely mutually exclusive when considering all cancer types, and particularly for endometrial adenocarcinoma, where both mutations are common." (PMID 27698488, 2016).
Infertility (3 papers, 2012 to 2023). "The deletion of Rarα resulted in 25.0% of females infertility due to vaginal closure, in which the mRNA (Ctnnb1, Bak and Bax) and protein (Cleaved Caspase-3) levels were significantly decreased, and Bcl2 mRNA levels were significantly increased in the vaginas." (PMID 37041518, 2023). "Conditional deletion of Ctnnb1 from the mesenchymal compartment of the uterus resulted in infertility stemming, in part, from complete failure of the uterus to decidualize." (PMID 22958837, 2012).
leiomyoma (3 papers, 2013 to 2022). A well-circumscribed benign smooth muscle neoplasm characterized by the presence of spindle cells with cigar-shaped nuclei, interlacing fascicles, and a whorled pattern. "Additionally, MED12 mutations have been implicated in the misregulation of WNT/CTNNB1 signaling, providing additional linage between two common mechanisms of leiomyoma development." (PMID 35203298, 2022). "The group also shows that WNT4 is overexpressed in CD34+/CD49b− leiomyoma cells and can stimulate leiomyoma cell proliferation via WNT/CTNNB1 signaling and AKT." (PMID 35203298, 2022). "Several WNT ligands and other mediators have been overexpressed in leiomyoma to activate the WNT/CTNNB1 pathway to enhance leiomyoma progression." (PMID 35203298, 2022). "Importantly, in human leiomyomas, most of these signaling pathways, such as upregulation of mTOR, TGFB1 and CTNNB1 pathway, deregulation of IGF-1 signaling in human uterine leiomyoma and inflammatory process involving TNF signaling have been reported." (PMID 33244099, 2020).
liposarcoma (3 papers, 2012 to 2024). A usually painless malignant tumor that arises from adipose tissue. "In a previous large-scale genomic sequencing study of soft tissue sarcoma specimens, that included 50 DD liposarcomas, a different CTNNB1 (T41I) mutation was described in a DD liposarcoma, including 3 other nonrecurring mutations (CDH1 (N238D), EPHA1 (A2127) and FBXW7 (E113fs))." (PMID 29731991, 2018). "In our study we also noted deleterious mutations in 7 other genes (CTNNB1 (R151H), MECOM (R208C), ZNF536 (T688M), EML4 (W729L), CSMD3 (P627S), PBRM1 (N639K), PPP1R3A (C788Y)) that have also not been described previously in WD/DD liposarcoma." (PMID 29731991, 2018).
liver cirrhosis (3 papers, 2013 to 2023). "This meta-analysis assessed the relationship between CTNNB1 mutations and clinicopathological parameters, including metastasis, vascular invasion, tumor size, differentiation, TNM stages, liver cirrhosis, and HBV/HCV infection." (PMID 37733676, 2023). "Additionally, CTNNB1 mutations were significantly associated with the differentiation grade, TNM stage, liver cirrhosis, and HBV infection." (PMID 37733676, 2023). "Additionally, we also assessed the relationship between CTNNB1 mutation and liver cirrhosis of HCC.4 studies evaluated the correlation of CTNNB1 mutation with liver cirrhosis." (PMID 37733676, 2023). "The focal adhesion pathway encompasses several genes, and KEGG analysis demonstrated that AKT1, CTNNB1, EGFR, FN1, JUN, and SRC were strongly related to curcumin compounds that might be influenced by liver cirrhosis in our study." (PMID 36297027, 2022).
liver tumor (3 papers, 2023 to 2025). "By binding to the lymphoid enhancer factor (LEF)/T-cell factor (TCF) family of DNA binding proteins, CTNNB1 enters the nucleus and regulates transcription of target genes such as c-mycor cyclin D1, resulting in proliferation and metastasis of liver tumor cells." (PMID 37733676, 2023).
metastasis (3 papers, 2011 to 2022). The spread or migration of cancer cells from one part of the body (where they first appeared) to another. "This suggests that CTNNB1 polymorphic variants may be a protective prognostic biomarker for NSCLC bone metastasis." (PMID 32453708, 2020). "Coincidentally, we observed that NSCLC bone metastasis patients with the AC/AA genotype of CTNNB1: rs1880481 have a longer PFS, which further indicates CTNNB1: rs1880481 may be a protective prognostic biomarker." (PMID 32453708, 2020). "Interestingly, our analysis revealed that the mRNA expressions levels of DPP4/CTNNB1/MET were more elevated in stage IV of THCA cancer, and were significantly elevated in metastasis tumor compared with the primary tumor." (PMID 35205190, 2022).
myocardial infarction (3 papers, 2022 to 2025). Gross necrosis of the myocardium, as a result of interruption of the blood supply to the area, as in coronary thrombosis. "In contrast, VEGFA (0.919; 0.847–0.998; P = 0.044), KIT (0.754; 0.575–0.988; P = 0.041), TNF (0.881; 0.796–0.974; P = 0.014), CTNNB1 (0.920; 0.858–0.986; P = 0.018), and GGT1 (0.887; 0.796–0.989; P = 0.030) were associated with lower risk of myocardial infarction." (PMID 41573742, 2025).
nasopharyngeal angiofibroma (3 papers, 2019 to 2025). "Various tumors harbor mutations in the CTNNB1 gene, including microcystic stromal tumors of the ovary (MST), soft tissue cribriform fibromatosis, juvenile nasopharyngeal angiofibroma, and sclerosing pulmonary hemangioma." (PMID 40115014, 2025). "Interestingly, other CTNNB1 ubiquitination motif-mutant tumors such as sinonasal glomangiopericytoma and nasopharyngeal angiofibroma show a high distance to IPM using TSNE analysis." (PMID 40676219, 2025).
nasopharyngeal carcinoma (3 papers, 2016 to 2022). A carcinoma arising from the nasopharyngeal epithelium. "One study showed that CTNNB1: rs1880481 was associated with poor radiotherapy efficacy in patients with nasopharyngeal carcinoma." (PMID 32453708, 2020). "Two core networks were generated by hub gene screening using the MCODE plugin of Cytoscape, and AKT1, CTNNB1, HSP90AA1, ESR1, CCND1, and EGFR were identified as key hub proteins, which may play an important role in the efficacy of icaritin in the treatment of nasopharyngeal carcinoma." (PMID 36467051, 2022).
nevus (3 papers, 2017 to 2022). Nevus (or naevus, plural nevi or naevi, from nævus, Latin for "birthmark") is the medical term for sharply circumscribed[1] and chronic lesions of the skin or mucosa. "CTNNB1 mutations occur in both benign and malignant melanocytic tumors with a deep penetrating nevus-like phenotype." (PMID 36077603, 2022). "To further investigate the role of CTNNB1 mutation in DPN, we used immunohistochemistry to evaluate β-catenin expression level and localization in DPN and common nevus controls." (PMID 28935960, 2017).
odontogenic tumors (3 papers, 2017 to 2022). "Dentinogenic ghost cell tumours (DGCTs) are odontogenic neoplasms characterised by a CTNNB1 mutation, ghost cell appearance, and dentinoid-like calcification." (PMID 35443664, 2022).
osteoarthritis (3 papers, 2021 to 2024). A noninflammatory degenerative joint disease occurring chiefly in older persons, characterized by degeneration of the articular cartilage, hypertrophy of bone at the margins and changes in the synovial membrane. "Secondly, studies have shown that miR-330-3p can slow cartilage degeneration in mice with osteoarthritis by targeting CTNNB1." (PMID 36980895, 2023). "In most cases, the expression of the studied genes, including CTNNB1 and WNTB2, was higher in patients with osteoarthritis compared to the group with fractures." (PMID 33357212, 2021).
Osteopenia (3 papers, 2020 to 2021). Osteopenia is a term to define bone density that is not normal but also not as low as osteoporosis. "The loss of CTNNB1 in osteoblasts leads to osteopenia and stabilization of CTNNB1 leads to high bone mass." (PMID 34006919, 2021). "Moreover, we found out a correlation between the CTNNB1 expression and the incidence of forearm and spinal fractures (R=0.717, p = 0.006 and R=−0.568, p = 0.043, respectively) in the subpopulation of patients with osteopenia and fractures (Group 2)." (PMID 33357212, 2021). "In the subpopulation of patients with osteopenia and fractures (Group 2), there was tendency to a positive correlation between the REL of CTNNB1 and TH BMD (R=0.533; p = 0.061) and TH T-score (R=0.522, p = 0.067)." (PMID 33357212, 2021).
polyposis (3 papers, 2015 to 2025). "We found the florid polyposis phenotype resulting from somatic Apc bi-allelic inactivation in mouse colon epithelium is potently inhibited by concurrent somatic inactivation of one Ctnnb1 allele." (PMID 26528816, 2015). "Accordingly, detection of a CTNNB1 mutation supports a sporadic origin, whereas an APC germline alteration and/or a polyposis phenotype suggests a hereditary form." (PMID 41227209, 2025). "CTNNB1 and APC mutations being exclusive, routine screening of polyposis is not a standard of care when the DT harbors CTNNB1 mutation." (PMID 35251801, 2022). "The findings on the lack of a demonstrable effect of Ctnnb1 hemizygous gene dosage in the mouse OEA model contrast with the findings above, where Apc-mutation-dependent polyposis in colon epithelium was dramatically suppressed by Ctnnb1 hemizygous inactivation." (PMID 26528816, 2015).
rectum adenocarcinoma (3 papers, 2020 to 2025). An adenocarcinoma arising from the rectum. "In APC mutation groups of COAD and rectum adenocarcinoma (READ), most SIGLEC family genes were significantly down-regulated; in the CTNNB1 mutation group of LIHC, all SIGLEC family genes were down-regulated (10 out of 14 achieved significance)." (PMID 33240817, 2020).
salivary gland neoplasm (3 papers, 2018 to 2025). Tumors of the SALIVARY GLANDS. "The detection of alternative drivers, such as CTNNB1 hotspot mutations typical of basal cell adenoma, also suggests that a subset of sialoblastoma may represent other salivary gland tumors presenting in infancy." (PMID 40906279, 2025).
seminoma (3 papers, 2015 to 2023). A radiosensitive malignant germ cell tumor found in the testis (especially undescended), and extragonadal sites (anterior mediastinum and pineal gland). "Association with seminoma was found for mutations in KIT, KRAS and NRAS and for putative oncogenic driver genes CBL, RAC1, PIK3CA, and CTNNB1 (analysed jointly due to lower frequency), p = 3.33 × 10−10, p = 1.41 × 10−6, p = 0.002, p = 0.009, respectively." (PMID 32366847, 2020). "However, we also observed significant associations between high expression of WNT activators (e.g., CTNNB1, FZD1, and FZD7) and poor survival of type II non-seminoma GCT patients, suggesting WNT signaling may be a common driver of adverse outcome in GCT patients across age groups." (PMID 37149691, 2023).
skin cancer (3 papers, 2014 to 2026). "Similar results were seen with genes in the beta catenin (Ctnnb1), hedgehog (Shh and Sufu), smoothen (Smo), patched 1 (Ptch1) and related genes which are involved in a common canonical pathway with skin cancers, notably basal cell type tumors, in mice." (PMID 25474466, 2014).
tuberculosis (3 papers, 2014 to 2024). A chronic, recurrent infection caused by the bacterium Mycobacterium tuberculosis. "Five polymorphisms were associated with tuberculosis susceptibility after Bonferroni correction: SFRP1 rs4736958, CTNNB1 rs9859392, rs9870255 and rs3864004 showed decreased tuberculosis risk; SFRP1 rs7832767 was related to an increased risk (OR = 1.81, 95% CI = 1.30–2.52, p = 0.010)." (PMID 27334567, 2016).
uterine tumors (3 papers, 2018 to 2026). "RNA-Seq-based clustering analysis of the three cases and a set of 193 uterine tumors showed that the CTNNB1-mutated cases clustered near LGESS cases." (PMID 41606383, 2026). "Mutations in CTNNB1, PTEN, and ARID1A were recurrent among the six uterine tumors (50%, 50%, and 33%, respectively), which is also consistent with previous reports from all-age-group uterine tumors." (PMID 29464067, 2018).
alcohol abuse (2 papers, 2023 to 2024). The use of alcoholic beverages to excess, either on individual occasions ("binge drinking") or as a regular practice.
alcoholic cirrhosis (2 papers, 2017 to 2021).
alcoholic liver diseases (2 papers, 2020 to 2022). A disorder caused by damage to the liver parenchyma due to alcohol consumption. "In contrast, the non-proliferative type was associated with CTNNB1 mutations, immune rejection, hepatitis C virus (HCV) and alcoholic liver disease, lower tumor grade, lower frequency of vascular invasion, and better prognosis." (PMID 36153509, 2022). "On the contrary, the nonproliferation class has been associated with CTNNB1 mutations, immune exclusion, HCV and alcoholic liver disease, low tumor grade, lower frequency of vascular invasion, and better prognosis." (PMID 32492896, 2020).
ampullary cancer (2 papers, 2017 to 2020). "The most frequent gene alteration in ampullary cancer was found in APC (23%), followed by CTNNB1 (9%), RNF43 (8%), CDH1 (1.9%), and WNT1 (1.3%)." (PMID 32764696, 2020).
atherosclerosis (2 papers, 2022 to 2024). A disease characterized by the build-up of fatty material and calcium deposition in the arterial wall resulting in partial or complete occlusion of the arterial lumen.
Barrett esophagus (2 papers, 2019 to 2021). Esophageal lesion lined with columnar metaplastic epithelium which is flat or villiform. "An altered Wnt-signaling activation has been reported during Barrett’s esophagus progression, but with rarely detected mutations in APC and β-catenin (CTNNB1) genes." (PMID 30841855, 2019).